TMPRSS2 (transmembrane serine protease 2)
Diseases named in the same sentence as TMPRSS2 in open-access papers (continued):
Sharing a sentence is not in itself a finding about the gene and the disease.
infection (continued). "As lung is the major target organ of SARS-CoV-2, the high co-expression of ACE2 and TMPRSS2 strongly suggests a high risk of infection of newborns through airborne transmission." (PMID 32298273, 2020). "Infection by SARS-CoV results in loss of TMPRSS2 expression in the airways and induces acute lung injury." (PMID 32764454, 2020). "It has been postulated that co-expression of ACE2 and TMPRSS2 underlies the susceptibility of other tissues to infection." (PMID 33125431, 2020). "In addition to its well-established role in respiratory viral infections, TMPRSS2 has been implicated in other infections, such as hepatitis C virus (HCV)." (PMID 39858469, 2025). "Similarly, the kidney has a high expression level of ACE2 and TMPRSS2 and is considered susceptible to infection." (PMID 40631549, 2025). "In this study, we examined the dynamics of household transmission of SARS-CoV-2, with a particular focus on age-related differences in seroprevalence and disease severity, as well as the potential contribution of ACE2 and TMPRSS2 expression to infection susceptibility." (PMID 40729397, 2025). "We also examine methodological approaches for assessing whether protease alterations contribute to increased susceptibility to infection, considering that TMPRSS2 exists in inactive (zymogen) and active forms." (PMID 41007801, 2025). "Given these dynamics, monitoring zoonotic reservoirs remains critical—not only to detect viruses already using key human receptors such as ACE2, APN, DPP4, or TMPRSS2, but also to identify emerging variants with pandemic potential before widespread human infection occurs." (PMID 40981424, 2025). "NL63 infection of Vero E6-TMPRSS2-T2A-ACE2 cells caused downregulation of ACE2 and TMPRSS2." (PMID 40431708, 2025). "Furthermore, analyses using TMPRSS2 KO intestinal organoids showed a dependence on TMPRSS2 for infection of Delta and Omicron BA.1 variant." (PMID 39601592, 2025). "In PCa, TMPRSS2 is directly regulated by AR transcription and regulated by androgen in vivo, which promotes tumor cell invasion and metastasis to distant organs and increases disease severity and infection risk." (PMID 40145441, 2025). "Three of these SNPs in TMPRSS2 (rs75603675, OR = 1.86, 95%CI = 1.29–2.66, p ≤ 0.001; rs4303795, OR = 1.98, 95%CI = 1.38–2.84, p ≤ 0.001 and rs8134378, OR = 2.59, 95%CI = 1.28–5.21, p ≤ 0.01) had a significant association with an increased risk of infection." (PMID 40296872, 2025). "Moreover, studies in TMPRSS2 knockout mice have shown reduced susceptibility and pathology following infection with influenza viruses or SARS‐CoV‐2, including highly transmissible variants such as Omicron." (PMID 40365759, 2025). "There remains an unanswered question as to whether a lower expression of ACE2 and/or TMPRSS2 on the surface of nasal and lung cells reduces susceptibility to infection in vivo." (PMID 38886986, 2024). "Additionally, predictive results for the risk of infection based on comparative analysis of the transmembrane serine protease 2 (TMPRSS2) sequence of these species were consistent with those obtained from the ACE2 sequence." (PMID 39030652, 2024). "previously studied the associations of the TMPRSS2 rs462574, rs456298, rs2298659, and rs12329760 (pV197M) polymorphisms with the risk of infection with SARS-CoV-2 in a Mexican population and reported that only rs462574 and rs456298 were associated with this association." (PMID 38601158, 2024). "Further, it has been suggested that inefficient TMPRSS2 usage might account for the inefficient infection of lung cells by the Omicron variant, which, in turn, might explain its attenuation compared to the previously circulating variants." (PMID 36851486, 2023). "Similar cell-type dependent TMPRSS2 subcellular pattern was previously reported for other cell types and may have influence in cell susceptibility to the infection." (PMID 37942479, 2023).
infection (continued). "Thus, in the context of the Delta variant, the histidine residue at position 655 supports the TMPRSS2-dependent membrane route of infection." (PMID 37243215, 2023). "This suggests TMPRSS2 is critically important for Omicron variant infection in murine airways." (PMID 37193304, 2023). "The latest research found that a TMPRSS2 inhibitor called N-0385 could effectively prevent the infection of the SARS-CoV-2 and its variants." (PMID 36329841, 2022). "We investigated which cognitive and sensorimotor functions are associated with the brain regions where ACE2/TMPRSS2 is overexpressed, hypothesising that they might be particularly affected by the infection." (PMID 35910337, 2022). "Since the cellular serine protease TMPRSS2 causes S-protein cleavage required for efficient entry and infection by SARS-CoV-2, it is possible that the presence of specific serpins in the HBEC ALI cultures of group low inhibits S-protein cleavage and thereby prevents infection." (PMID 35532162, 2022). "Taking into account the role of ACE2 and TMPRSS2 in the development of infection, it can be concluded that by influencing the activity of these proteins it is possible to limit the risk of the virus entering the host cells and spreading the infection." (PMID 35739949, 2022). "Furthermore, a change in the expression profile of ACE2 and TMPRSS2 needs to be evaluated in the nasal epithelium since that is implicated as a portal for initial infection and transmission." (PMID 35677336, 2022). "This would be reasonable if it is assumed that T-allele carriers express more genes that could result in increased TMPRSS2 activity leading to increased infection susceptibility." (PMID 36457338, 2022). "SARS-CoV-2 variants still use ACE2/TMPRSS2 for infection, although with different affinities." (PMID 35708858, 2022). "Genetic variants related to reduced TMPRSS2 expression may confer less individual susceptibility to infection with a better disease outcome." (PMID 36012436, 2022). "This would make sense, if one assumes that T-allele carriers have a higher gene expression (GTEx portal), which could enhance TMPRSS2 activity and so may result in a higher infection susceptibility." (PMID 33968142, 2021). "However, no cell clusters from the liver, stomach, and pancreatic islets data show high ACE2 and TMPRSS2 expression levels, which demonstrates a low infection risk." (PMID 33401657, 2021). "Our analysis suggests that at the infection stage DS individuals might be more susceptible to infection due to triplication of TMPRSS2, that primes the viral S protein for entry in the host cells." (PMID 33479353, 2021). "Therefore, even if the spike protein in these SARS-CoV-2 variants binds to ACE2, these ingredients (SDS, TDS, LMT, LSS, GCU, and TXA) will inhibit TMPRSS2-dependent cell membrane fusion and thereby prevent infection of these SARS-CoV-2 variants to host cells." (PMID 34534255, 2021). "Besides, age-, sex-, and comorbidity-associated variation in infection rate correlates with the expression rate of TMPRSS2 in those groups." (PMID 34336361, 2021). "Interestingly, the allele delC of the top significant eQTL (rs35074065) associates with higher expression of TMPRSS2 compared to the reference allele and is less frequent among East Asians, suggesting a protective role against the infection in this population." (PMID 32849840, 2020). "Furthermore, in mouse knock-out (KO) mutants, it was shown that Tmprss2-deficient (Tmprss2−/−) mice are highly resistant to infections with H1N1 and monobasic H7N9, but only weakly to H3N2." (PMID 30084768, 2018). "Thus, individuals with diminished TMPRSS2 expression may still be susceptible to infection through endosome-dependent pathways." (PMID 40969755, 2025).
infection (continued). "Although more viruses possibly enter into cells during initial infection in the respiratory tract due to overexpression of TMPRSS2 and other susceptibility genes, hyper-responsiveness to IFN-I could potentially dampen subsequent viral replication in Dp16;ACE2 mice." (PMID 38540156, 2024). "However, some studies have concluded that the lower severity of the Omicron-induced infection could be due to its slower replication in the transmembrane serine protease 2 (TMPRSS2) than in previous variants." (PMID 36766664, 2023). "Moreover, some recent studies suggest that the SARS-CoV-2 Omicron BA.1 and BA.2 variants, which together accounted for most of the new infections in the first half of 2022, preferentially use the endosomal entry pathway instead of TMPRSS2-dependent cell surface entry." (PMID 36985290, 2023). "In addition, TMPRSS2 is also expressed in the aerodigestive tract, facilitating the entry of coronavirus particles into cells by cleaving the spike protein and making people more susceptible to infection of SARS-CoV-2." (PMID 35558557, 2022). "Additionally, we found that during the fetal development, ACE2 and TMPRSS2 were enriched in pathogen infection-associated pathways and may involve in the biological processes related to T-cell activation." (PMID 35154056, 2022). "Mutations in TMPRSS2 may render these animals less susceptible to infection by SARS-CoV-2." (PMID 33020502, 2020). "Interestingly, others revealed that ACE2 and TMPRSS2 are co-expressed in a portion of human epiblast cells, suggesting that early human embryos could be susceptible to infection by SARS-CoV-2." (PMID 32722449, 2020). "Vero-E6/TMPRSS2 were pre-incubated with the peptides (1–50 μM) for 2 h prior to infection with SARS-CoV-2." (PMID 41599331, 2026). "Strikingly, we found that disruption of LGMN–but not TMPRSS2–lead to significant decreases in replication competent SARS-CoV-2 infection, suggesting that LGMN acts independently of TMPRSS2 to promote infection." (PMID 40674406, 2025). "Epithelial cells (CaCo-2) were stimulated with SARS-CoV-2 spike protein, treated with native VIP and analyzed to investigate the mRNA and surface expression of ACE2 and TMPRSS2, the enzyme activity of TMPRSS2 and the infection rate by a SARS-CoV-2 pseudovirus." (PMID 40141308, 2025). "To that end, we transduced cell lines with endogenous LGMN expression with lentiCRISPRv2 constructs encoding Cas9 plus gRNAs targeting either ACE2, TMPRSS2, or LGMN and subjected the knock-out cell lines to infection with replication competent SARS-CoV-2." (PMID 40674406, 2025). "Inhibition of TMPRSS2 is a viable treatment method for reducing infection rates since it directly affects viral entry processes." (PMID 40297833, 2025). "We uncover a mechanism that LL37 can remarkably inhibit the SARS‐CoV‐2‐induced membrane fusion activity with host cells and infection through binding to the spike S2 subunit and blocking TMPRSS2‐mediated S2' priming process." (PMID 40375579, 2025). "Taken together, ACE2 and TMPRSS2 are the main receptors necessary to facilitate infection in the endometrium." (PMID 39666439, 2025). "Studies have demonstrated that TMPRSS2 enhances the spread of viruses through localized infections and facilitates syncytium development, enabling effective cell-to-cell dissemination while escaping immune responses." (PMID 40297833, 2025). "Although the cleaved and closed conformation cannot readily recognize ACE2, the infection was quick when TMPRSS2 was also present on target cells." (PMID 41257850, 2025). "Caco-2 and Calu-3 cells have been used previously in SARS-CoV-2 research over primary, normal cell lines due to their expression of ACE2 receptors as well as the protease TMPRSS2, which make them permissible to infection." (PMID 40486909, 2025). "It is unclear if TMPRSS2 co-localizes with ACE2 in human kidney proximal tubules or if separate localizations explain observations of low primary infection in kidney epithelium." (PMID 39382598, 2025).
infection (continued). "The SC2-VLP supports single-round infection of HEK293T cells co-expressing ACE2 and TMPRSS2, with infection efficiency quantified by measuring firefly luciferase (Fluc) reporter activity in target cells." (PMID 40972091, 2025). "Especially in combination with reducing the surface expression of ACE2 and TMPRSS2 and the reduction of the activity of TMPRSS2, the infection of the cell is impaired by VIP." (PMID 40141308, 2025). "The S protein of wild-type SARS-CoV-2 is cleaved into the S1 and S2 subunits by the furin enzyme and transmembrane serine protease 2 (TMPRSS2) during the infection process." (PMID 40103818, 2025). "Despite numerous studies demonstrating the role of TMPRSS2 in the development of SARS-CoV-2, the current findings enhance the understanding of how these gene polymorphisms influence susceptibility to infection." (PMID 40296872, 2025). "OITV 321/2022 replicated in Vero, Vero-RcACE2, and VeroE6/TMPRSS2 cells, with apparent cell detachment at 4–5 days post-infection (dpi)." (PMID 41217194, 2025). "Initial validation confirmed efficient infection of 293T-ACE2/TMPRSS2 cells by the G614D pseudovirus and successful pseudovirus production in VeroE6/TMPRSS2 cells." (PMID 40862555, 2025). "One of the key proteases that cleave and activate viral HA protein is TMPRSS2, a critical component of the virus fusion with the host cell membrane and for initiating infection." (PMID 40297833, 2025). "TMPRSS2 infection enhancement is dependent on its serine protease activity, which can be blocked pharmacologically or by mutational deletion of the HDS catalytic triad." (PMID 40981424, 2025). "Different expression patterns of TMPRSS2 have been reported, mainly in lung tissue, the primary site of infection." (PMID 40296872, 2025). "Cell binding assay showed that FH significantly reduced lentiviral pseudoparticle binding to and infection of A549-hACE2+TMPRSS2 cells, whereas FP and TSR4 + 5 enhanced cell binding and infectivity." (PMID 40895576, 2025). "The major pathway of infection involves the proteolytic processing of the S protein by the transmembrane serine protease 2 (TMPRSS2), enabling virus host membrane fusion and release of the viral RNA in the cytosol." (PMID 40170841, 2025). "It has been reported that TMPRSS2 knockout mice were protected from severe pathogenesis upon infection with MERS-CoV or SARS-CoV." (PMID 39599912, 2024). "Angiotensin-converting enzyme 2 (ACE2) and transmembrane serine protease 2 (TMPRSS2), the entry point for SARS-CoV-2, are expressed in the sustentacular cells being more susceptible than ONs to early infection [89••, 90, 91••]." (PMID 38492160, 2024). "Comparing TMPRSS2 levels, a significant difference was observed before infection, where symptomatic patients had higher protease expression levels (p < 0.001) than those among asymptomatic patients." (PMID 38606293, 2024). "TMPRSS2 is essential for facilitating the infection process, as it cleaves the spike protein of SARS-CoV-2, enabling the virus to bind to its cell surface receptor, angiotensin converting enzyme 2 (ACE2), and gain entry into cells." (PMID 39224588, 2024). "Viral replication and HA cleavage in infected Calu-3 human airway cells, however, were exceptionally dependent on the presence of catalytically active TMPRSS2, suggesting that cleavage by other TTSPs plays only a minor role, if any, during infection." (PMID 39599912, 2024). "Research has indicated that eliminating TMPRSS2 from the respiratory system impacted the initial infection site and viral dissemination in the airways, consequently diminishing lung pathology in SARS‐CoV and MERS‐CoV cases." (PMID 38923119, 2024). "To quantify cell fusion, we used Vero-TMPRSS2 cells which are engineered to express ACE2 and TMPRSS2, allowing for efficient infection." (PMID 38361824, 2024). "Low expression of TMPRSS2 in Vero E6 cells is associated with permissibility of the cells to XBB-derived and BA.2.86.1 infection." (PMID 38480689, 2024).
infection (continued). "In recent decades, another group of TMPRSS2-activated viruses, three members of the Coronaviridae family have emerged, each capable of inducing severe infections in humans." (PMID 39025978, 2024). "We first examined the growth characteristics of these variants and the Wu-2020 strain used in this study in Vero E6/TMPRSS2 cells at a multiplicity of infection (MOI) of 0.001, and found that the growth kinetics were almost comparable among strains." (PMID 39717778, 2024). "When VeroE6 expressing human ACE2 and TMPRSS2 (VeroE6/hACE2/TMPRSS2) were infected with a viral titration of WT strain, all tested infection doses reduced the cell viability, showed high CPE and high viral litres." (PMID 39130731, 2024). "While earlier variants such as Delta require the transmembrane serine protease 2 (TMPRSS2) for activation, Omicron infection can occur independently of this protein, allowing Omicron to infect cells that lack TMPRSS2." (PMID 39095802, 2024). "For cell lines exhibiting syncytium formation after PMV/Bat35 infection—Vero, VeroE6/TMPRSS2, Rc, and iMylc-D05-s-ML2 cells—TCID50 was calculated." (PMID 40303027, 2024). "The ACE2 enzyme is stimulated by the transepithelial serine protease type II TMPRSS2 or cathepsin L. Additional receptors involved in the infection process have also been described thus far: CD147/EMMPRIN/Basigin, Axl and Neuropilin-1 (NRP1)." (PMID 38592169, 2024). "SARS-CoV-2 binds to the angiotensin-converting enzyme 2 (ACE2) receptors and transmembrane serine protease 2 (TMPRSS2), enabling the infection of the retina and the CNS, with viral RNA detected even in the cerebrospinal fluid." (PMID 38541228, 2024). "We used ΔN SCIPs to infect 293T-ACE2/TMPRSS2 cells expressing N-D5 or a vector control (CMVpA) for 4 hours and measured NanoLuc luminescence 24 hours after infection." (PMID 39571001, 2024). "Small-molecule therapies can stop viral replication following infection, and our study proposes that vicenin-2, neohesperidin, naringin, and rhoifolin can act as TMPRSS2 antagonists and viral entry inhibitors, subject to experimental validations." (PMID 39003338, 2024). "It is thought that viruses that express spike with an additional basic amino acid(s) in the furin cleavage recognition site than WA1 (Alpha, Delta, Omicron) would likely use the TMPRSS2-dependent plasma membrane route of infection." (PMID 38477472, 2024). "Like Omicron variants, BA.2.86 can enter cells via endosomes as well as through TMPRSS2 but prefers ACE2-mediated infection in concordance with authentic BA.2.86 infection results." (PMID 39071099, 2024). "For example, α-1-antitrypsin inhibits TMPRSS2, which is required for S protein cleavage, thus aggravating the infection." (PMID 39062796, 2024). "Collectively, our in vitro data demonstrates the novel Mpro/TMPRSS2 bispecific inhibitor TMP1 not only suppresses the infection of SARS-CoV-2 but also potently protects against other seasonal and highly-pathogenic coronaviruses." (PMID 39606435, 2024). "The human coronavirus HKU1 spike (S) glycoprotein engages host cell surface sialoglycans and transmembrane protease serine 2 (TMPRSS2) to initiate infection." (PMID 38260518, 2024). "Transmembrane protease serine 2 (TMPRSS2) is an important drug target due to its role in the infection mechanism of coronaviruses including SARS-CoV-2." (PMID 38157015, 2024). "Conformational changes then lead to priming of the viral spike protein by proteases like transmembrane protease serine 2 (TMPRSS2), which results in fusion pore formation and, ultimately, cell infection." (PMID 38334597, 2024). "The low levels of expression of both ACE2 and TMPRSS2 are important for ensuring the placenta, and thereby the foetus, are protected from infection." (PMID 39640372, 2024). "The study concluded that although NRP1 did not promote infection itself, its coexpression with ACE2 and TMPRSS2 enhanced infection." (PMID 38887342, 2024).